CD4 (CD4 molecule)
Diseases named in the same sentence as CD4 in open-access papers (continued):
Sharing a sentence is not in itself a finding about the gene and the disease.
co-infection (continued). "Patients were of Zulu/Xhosa background and represent a sample that differs significantly in gender, age, CD4 cell count nadir and co-infection from most US and European cohorts used in previously published analysis on CD4 cell restoration." (PMID 22348047, 2012). "One possible explanation is that TB co-infection results in additional CD4 cell count suppression, which resolves with treatment of both infections." (PMID 22348047, 2012). "The study included ten eyes of nine patients; one patient with HIV co-infection which was being successfully treated with HAART (CD4 count > 500 cells/mm3 and undetectable viral load) presented with disseminated herpes zoster virus infection and bilateral ARN." (PMID 22947428, 2012). "The aim of this study was to explore the effects of HCV co-infection on virological effectiveness and on CD4+ T-cell reconstitution in patients with an early and sustained virological response after HAART." (PMID 22703595, 2012). "HIV/HCV co-infection, nadir CD4 + T-cell count < 200 cells/μL and drug addiction were independent predictors of severe BMD." (PMID 22894751, 2012). "The aim of this study was to explore the effects of HCV co-infection on virological effectiveness and on CD4+ T-cell recovery in patients with an early and sustained virological response after HAART." (PMID 22703595, 2012). "The majority of our patients were young females, with low CD4 cell nadir (below 100 cells/mm3) and high prevalence of TB co-infection at presentation, consistent with the population profile most affected in Sub-Saharan Africa." (PMID 22348047, 2012). "We found that HIV/HCV co-infection group had lower Th1/Th2 ratio, the CD4+ T lymphocyte count and HIV viral load was higher than HIV mono-infected group." (PMID 22533731, 2012). "Whilst the other was a female Burmese heterosexual with CD4 counts >200 cells/ mm3 and experiencing co-infection with cryptococcosis." (PMID 22347442, 2012). "In our study, 26.96% of the patients reported having cytomegalovirus co-infection with median CD4+ counts 147 cells/mm3." (PMID 21396133, 2011). "CD4 cell count below 50/mm3 and hsCRP > 5 mg/L were associated with hyperferritinemia after correction for gender, degree of anemia, and HCV co-infection." (PMID 21827653, 2011). "CD4+ T cells mediate immunity during FV as well as FV/LDV+ co-infection, as comparable results are obtained in CD4-depletion experiments using FV alone or FV/LDV+ infected mice." (PMID 21943070, 2011). "TB therapy leads to measurable decreases in immune activation in persons with HIV/TB co-infection and CD4 counts >350 cells/mm3." (PMID 20179751, 2010). "In the final model, CD4 count slope was associated with age, concurrent HIV VL and CD4 count, disease stage, hepatitis B or C co-infection, and time since cART initiation." (PMID 21182796, 2010). "Acknowledging the improved outcomes achieved with ART, WHO guidelines have moved beyond 2006 recommendations guided by CD4 count to now recommend ART in all people with TB-HIV co-infection." (PMID 21605474, 2010). "Several consequences of P. cynomolgi and SIV co-infection of rhesus macaques were observed, including an increased risk of SIV disease progression and accelerated CD4 T-cell decline." (PMID 19774084, 2009). "Further investigation is needed to clarify the role of CD4+ T-cell help in affecting the frequencies of HCV-specific CD8+ T-cells in HCV/HIV-1 co-infection." (PMID 18941622, 2008). "In patients with HCV/HIV co-infection, CD4+ T cell proliferative immune responses to HCV antigens are lower than in HCV monoinfected patients." (PMID 25977607, 2008). "In particular, HLA-DR expression on CD4 T cells was correlated with CD4 T cell count, viral load and coinfections." (PMID 16792805, 2006). "fragile co-infection but were unassociated with peripheral parasitemia and CD4+ T cell frequencies." (PMID 41660411, 2026). "Among the pediatric TB/HIV co-infection patients, 20.5% had a decreased CD4 T-cell count." (PMID 40568707, 2025).
co-infection (continued). "Unlike other opportunistic diseases associated with HIV, post-cART immune reconstitution is still severely impaired in VL/HIV co-infection, as shown by low CD4+ T-cell counts even in patients with an undetectable HIV viral load and clinical remission after treatment of VL." (PMID 40145085, 2025). "HIV and HTLV-1 co-infection increases mortality despite higher baseline CD4+ counts." (PMID 40284988, 2025). "Alternatively, higher rates of recombination may be driven by differences in target cell availability—the larger pool of activated CD4+ T cells during early infection may facilitate higher rates of cellular co-infection." (PMID 40740855, 2025). "Conversely, Th17 subset was largely consistent with previous studies, showing earlier exhaustion in HIV infection, and its functionality was severely compromised, consistent with the early loss of IL-17–producing CD4+ T cells in HIV infection and their sustained exhaustion during co-infection." (PMID 41394852, 2025). "Considering parasitic co-infections and cytokine profiles in relation to the CD4 count in HIV management remains important, especially in endemic regions, to develop more targeted interventions that could improve patient outcomes." (PMID 40046043, 2025). "This decline could be critical for individuals with reduced CD4 counts who present an increased risk of severe complications and mortality due to infection, such as PWH with MPXV coinfection." (PMID 41204857, 2025). "Moreover, the factors leading to poorer clinical outcomes due to co-infection include the impact that HCV has on the recovery of CD4+ cells in patients undergoing ART." (PMID 39813525, 2025). "Coinfection of MPXV and HIV is associated with worse clinical outcomes, including more severe mpox disease, prolonged time to healing of lesions, and higher mortality, particularly among those with low CD4 cell counts and high HIV viral load." (PMID 40498594, 2025). "The co‐infection can trigger a state of CD4+ T cell activation, which facilitates HIV infection." (PMID 40066241, 2025). "Compared to the reference range of 410–1590/μL for healthy adults, the median level of peripheral blood CD4+ T lymphocytes in the HIV-MTB co-infection group was much lower at 78.5/μL (IQR = 153.75), while the median level in the MTB mono-infection group was 673/μL (IQR = 402)." (PMID 39205309, 2024). "However, our study identified that specific factors such as CD4+ cell count below 560 cells/μL and HPV 16 or 18 co-infection were associated with multiple HR-HPV infections." (PMID 39070626, 2024). "Due to the fact that both HTLV-1 and HIV-1 can target CD4+ T cells for productive infection, co-infection or superinfection may also occur at the cellular level in co-infected patients." (PMID 38787201, 2024). "Co-infection or superinfection of an HIV-1-infected CD4+ T cell may occur when two viruses with the same cellular tropism enter the same cell together or one after the other, respectively." (PMID 38787201, 2024). "Since adenoviral infections may actually increase CD4+ T cells, it is plausible that adenoviral coinfection may actually be beneficial in Cryptosporidium infections." (PMID 39339972, 2024). "However, having a serum CD4+ cell count below 560 cells/μL and a co-infection with either HPV 16 or 18 genotype were significantly associated with the detection of multiple HR-HPV infections." (PMID 39070626, 2024). "Our results clearly show that the increased frequency of CD8+ T cells in the BAL and lungs of D1MT+cART-treated RMs was not just due to the lower frequencies of CD4+ T cells by SIV coinfection, as the absolute number of both CD4+ and CD8+ T cells increased after D1MT+cART treatment." (PMID 39114981, 2024). "Indeed, in vitro co-infection/superinfection of CD4+ T cells with HIV-1 and HTLV-1 can be obtained, resulting in pseudotyping of HIV-1 virions with HTLV-1 Env." (PMID 38787201, 2024).
co-infection (continued). "Furthermore, we observed in our population that HCV co-infection increased the likelihood of being diagnosed with a CD4 count < 200 cells/μL by 10-fold." (PMID 38338246, 2024). "However, most studies published on helminth-Tg co-infections focus on IFN© production by conventional T cells (CD4+ and CD8+ T cell), with much less known about the role of other lymphocyte populations (e.g. γδ T and NKT cells)." (PMID 38950025, 2024). "The explanation could be that with a longer duration of antiretroviral therapy (ART), there is a potential for an increase in CD4 count, improved viral suppression, and a reduced likelihood of co-infection compared to the early stages of ART initiation." (PMID 38740783, 2024). "The univariate logistic regression model study results indicated that age, literacy level, marital status, HIV infection route, and initial CD4+ T-lymphocyte count were the factors impacting the co-infection of HIV/HBV among newly diagnosed HIV-infected subjects in 2023." (PMID 38787219, 2024). "To investigate the contribution of CD4+ T-cell counts to the observed effects of HIV co-infection on Mtb transmission, we repeated our phylodynamic analyses on sequences from South Africa and Uganda, with subpopulations defined by CD4+ T-cell counts (lower resp." (PMID 38696531, 2024). "Abundant basic research indicates that the occurrence and development of HIV-associated lymphoma are indirectly related to CD4+ T-cell damage after HIV infection, chronic B-cell activation, and oncovirus coinfection, as well as directly related to proteins and RNA encoded by HIV." (PMID 39329948, 2024). "Co-infection reduced the proportion of CD4+, CD3+, and CD8+ T cells in the granuloma tissues of patients, suggesting that HIV infection could lead to a decrease in the number of lymphocytes in tuberculous granuloma tissues." (PMID 39205309, 2024). "In fact, a high CD4 T-cell count could be an abnormal increase in case of co-infection between HIV-1 and HTLV-1 conferring false immunity to the patients, as recently reported in a similar population type." (PMID 38257785, 2024). "HIV infection decreases CD4+ T cell levels markedly increasing Mtb co-infections." (PMID 38799434, 2024). "The identified risk factors, such as HBV/HCV co-infection, HIV RNA load, CD4+ T-cell count, and Neu and Lym levels, may have synergistic effects on SSI risk." (PMID 38988810, 2024). "To assess the impact of cART + 3HP on T cellactivation, we studied expression of HLA-DR and CD69 on CD4+ T cells in BAL atweek 11 post Mtb infection (or 2 weeks post SIV co-infection, prior toinitiation of cART + 3HP) and at necropsy (end of 12 weeks of cART + 3HP treatment) in all4 study groups." (PMID 39257997, 2024). "Our study identified several risk factors associated with an increased risk of liver injury following TB treatment, including a CD4 count less than 200 mm3 in HIV-infected individuals, pre-existing hepatitis, previous TB treatment history, hypo-albuminemia, and HIV co-infection." (PMID 39502524, 2024). "This is especially of importance in areas where HIV coinfections may influence the antibody level due to low CD4 counts." (PMID 39108464, 2024). "An important feature of HIV-1, favoring co-infection/superinfection with related or unrelated viruses, is its capacity to establish latent infections, especially in long-lived CD4+ resting memory T cells, thus providing a cellular reservoir infectable by other lymphotropic viruses." (PMID 38787201, 2024). "Review of included studies demonstrated that poor medication adherence, high HIV viral load, low CD4 level at the baseline and during therapy, co-infection presence, and advanced clinical stage of infection were the most prevalent factors associated with drug resistance and virological failure." (PMID 37884997, 2023).
co-infection (continued). "Furthermore, we found that advanced age, high CD4 cell count, and positive HBeAg at baseline were significantly associated with a higher rate of HBsAg clearance in patients with HIV/HBV coinfection after long-term TDF-containing ART." (PMID 36844414, 2023). "Additional co‐infection with other chronic viruses may exacerbate the phenotype; for example, HIV and CMV co‐infection leads to inversed CD4/CD8 ratio and has a particularly high cardiovascular risk." (PMID 36378563, 2023). "Another possible explanation is that HCV co‐infection may affect the CD4 count, which decreases after HCV seroconversion in PLWH compared with PLWH only." (PMID 37221951, 2023). "Our findings hypothesized that the expansion of TGF-β-secreting CD4+ Treg cells in HIV/TB co-infection played an important role in inhibiting T-cell immunity against MTB." (PMID 37483385, 2023). "Co-infection HIV and TB are also highly associated with a decrease in CD4 cell count over time." (PMID 38087261, 2023). "When we quantified Mtb (ESAT64-17)-specific CD4+ T cells via MHC-II tetramer straining one month following co-infection with SCV2, the frequency of antigen-specific CD4+ T cells was unchanged between mice infected solely with Mtb or those co-infected with SCV2." (PMID 37720210, 2023). "Demographic factors, co-infection, baseline CD4 cell level, abnormal immune activation, and cytokine dysregulation may all affect immune reconstitution." (PMID 37608956, 2023). "Moreover, CD4+ cell count has been introduced as a marker for detection of HIV co-infection with HBV and HCV." (PMID 37942194, 2023). "Recently, several studies in Caucasians and Thailand found that ethnicity, HBV viral load, CD4 cell count, HBeAg, and quantification of HBsAg were significantly associated with HBsAg clearance among patients with HIV/HBV coinfection treated with long-term TDF-containing ART." (PMID 36844414, 2023). "People living with HIV who died with suppressed viral loads were older, had higher CD4 counts and had additional comorbidities like hypertension, obesity, and diabetes, while those with detectable HIV VLs had significant coinfections or HIV-associated malignancies." (PMID 36751479, 2023). "Our findings suggested that in HIV/TB co-infection, the enhanced granzyme A production in both CD4+ CTLs and CD8+ CTLs might be critical for the clearance of viruses and MTB." (PMID 37483385, 2023). "Effective control of B. burgdorferi infection depends on a Th2 CD4+ T cell response within regional lymph nodes, and co-infection with B. microti may influence T cells toward a TH1 response." (PMID 37764145, 2023). "Next, we asked whether co-infection with SCV2 at 16 weeks post Mtb infection could negatively impact the existing Mtb-specific CD4+ or CD8+ T cell responses." (PMID 37720210, 2023). "By multivariate analysis, in TN PLWH, 2-DR had a lower risk of discontinued treatment (hazard ratio [HR]: 0.23, 95% CI: 0.05 to 1.1, p = 0.07), adjusted by age, sex, rate of PLWH with HCV coinfection, CD4+ T-cell count (cells/μL) and Log VL at study treatment initiation." (PMID 37773939, 2023). "In addition, they confirmed that having less than 200 CD4/mm3 and HIV/HCV coinfection were associated with a worse response." (PMID 37243000, 2023). "Nevertheless, both studies identified that curtailed CD4+ T cell responses in Mtb-infected lungs are a main cause of the progression to severe TB regardless of the viral coinfection order." (PMID 35672321, 2022). "Third, STI–HIV coinfection can usually reduce the CD4+ T cell count and enhance the HIV viral load in blood plasma and genital secretions, which might decrease the effectiveness of antiretroviral therapy (ART)." (PMID 35027093, 2022). "At the same time, the presence of active HBV infection will affect the viral immunological status of patients with HIV/HBV coinfection, which is characterized by the low number of CD4+ T cells at the onset and the slow recovery of CD4+ T cell count after antiretroviral treatment." (PMID 35634301, 2022).
co-infection (continued). "Similarly, HIV patients with CD4+ T cells count less than 350 cells/mm3 were more likely to have HIV-HBV-HCV co-infection as compared to those with CD4 count equal to and more than 350 cells/mm3 (AOR 13.84, 95% CI: 2.90,66.10)." (PMID 35239716, 2022). "It is speculated that, during herpesvirus/HIV co-infection, CD4 T cell proliferation increases, thereby expanding the target cell type susceptibility to HIV infection, resulting in a high HIV viral load." (PMID 36016445, 2022). "The CD4+ T lymphocyte count of nine patients in group 1 was below the normal level (CD4+T cells < 410 cells/μL), and all nine patients had disseminated infections, persistent infections, and co-infections." (PMID 35641599, 2022). "Our data suggested that HIV/TB co-infection resulted in a marked increase of CD4+CD8+ T cells." (PMID 36619740, 2022). "Patients who had low CD4 (<200 cell/ul), with a poor level of adherence, BMI<18.5kg/m2, did not take IPT prophylaxis, bedridden functional status, and baseline WHO stage III or IV are associated with TB co-infection among adult HIV positives." (PMID 35921384, 2022). "This is critical in the setting of HIV coinfection since HIV-induced increase in TB risk is mainly attributed to loss of CD4 T cell functions and the residual anti-mycobacterial T cell responses are dependent on non-CD4 T cell effector functions." (PMID 36726992, 2022). "By multivariate logistic regression analysis, age > 30 years, high viral load (> 100,000 copies/mL), low CD4+ T cells count (< 200 cells/μL), HCV coinfection, and TB infection were associated to the development of CKD (Cox and Snell R-squared: 0.471; p = 0.001)." (PMID 34556049, 2021). "The findings of this study show that while EBV and HPV infections may synergistically target miR-21 and miR-200c, HSV-2 and its related co-infections may target miR-182 and CD4+ T-cell activity to initiate EMT." (PMID 33824853, 2021). "Remarkably, the presence of detectable viral loads (median = 17000 copies/μL) and CD4+ cells/μL (median = 217) at co-infection diagnosis in our entire sample of T. cruzi/HIV infected patients emphasizes the need of early diagnosis of co-infection and introduction of effective antiretroviral therapy." (PMID 34591866, 2021). "Likewise, immunological discordant response was associated with tuberculosis co-infections (p = 0.016), hepatitis B virus co-infections (p = 0.05) and low CD4+ count (≤100 cells/μl) at baseline (p = 0.026)." (PMID 34118891, 2021). "Also, looking at the mean value of the CD4+ count of 303.08, shows that the co infection of HIV with HCV inhibits the recovery of the CD4+ cells since the patients have been on antiretroviral (HAART) for nothing less than six months." (PMID 35222562, 2021). "Low CD4 cell counts have been associated with lower BMD, as have coinfection with viral hepatitis." (PMID 33968446, 2021). "This implies low CD4 cell count is potential determinant for TB/HIV co-infection." (PMID 35222561, 2021). "CD4 T cells are responsible for the cytokine response, and the reduced immunopathology reported in a rhinovirus and influenza co-infection model may correlate well with a reduced CD4 T cell count." (PMID 34452495, 2021). "However, some studies have longitudinally characterised the HDV CD4+ T cell response during the primary HBV/HDV coinfection or acute HDV superinfection of HBsAg carriers using standardised CD4+ T cell assays." (PMID 34308324, 2021). "Furthermore, since clinical variables were associated with TB/HIV co-infection, health professionals should care for patients who are in WHO clinical stage III, and patient who had lower CD4 counts." (PMID 35222561, 2021). "In HSV and HIV co-infections, CD4+ TRM persisting in the dermis support HIV replication." (PMID 33668777, 2021).